FAM3C (FAM3 metabolism regulating signaling molecule C)
Diseases named in the same sentence as FAM3C in open-access papers (continued):
Sharing a sentence is not in itself a finding about the gene and the disease.
tumor (continued). "From the heatmap of the log (fold change (FC)) of FAM3 family genes in 24 cancers, we can see that FAM3A and FAM3C showed a tendency to be highly expressed in the tumor tissues." (PMID 37704682, 2023). "FAM3C encodes for the interleukin-like EMT inducer (ILEI) protein, a secreted factor that can regulate tumor progression." (PMID 33596971, 2021). "FAM3C-related ligand-receptor pairs, like LAMP1_FAM3C, FAM3C_CLEC2D, CXADR_FAM3C, were slightly upregulated in ductal-tumor and malignant cells." (PMID 35087839, 2021). "Collectively, these findings together suggested that FAM3C likely initiates the crosstalks among YY1, HSF1 and Akt, finally causing excessive Akt activation to trigger tumour growth and invasion." (PMID 30887707, 2019). "In the current study, we found that 70.0 % of ESCC patients showed elevated FAM3C expression in their tumor tissues compared with the normal counterparts." (PMID 26498278, 2015). "The median fold change of FAM3C (2.28) in ESCC tumor specimens was used as a cutoff value to divide all 107 patients into two groups: high expression group (n = 53) and low expression group (n = 54)." (PMID 26498278, 2015). "In the present study, we, for the first time, reported that FAM3C expression was upregulated in ESCC, which was associated with aggressive tumor behavior, metastasis, and poor clinical outcome." (PMID 26498278, 2015). "FAM3C promotes the EMT of tumor cells through the JNK-ZEB1/Snail signaling pathway." (PMID 40568576, 2025). "Furthermore, we demonstrated that FAM3C up-regulation in neutrophils is through tumor-derived TGFβ1." (PMID 37056931, 2023). "While our in vitro findings show that uptake of FAM3C through EVs could regulate tumor localization, the mechanism of EV transmission remains unclear." (PMID 36632230, 2023). "Stratification of patients based on high FAM3C expression in plasma EVs may pave the path for developing strategies against widespread tumor colonization." (PMID 36632230, 2023). "So, we further investigated the effect of FAM3C expression level on tumor cellular functions." (PMID 37704682, 2023). "FAM3C/ILEI is an important cytokine for tumor progression and metastasis." (PMID 37226685, 2023). "FAM3C is a potent inducer of tumor metastasis which regulates EMT through TGF-β signaling 22-24, and is associated with poorer prognosis in several cancer types 17, 25, but its role in NSCLC remains unclear." (PMID 36632230, 2023). "The expression of FAM3C in tumor tissue was significantly higher than normal (P < 0.05)." (PMID 37704682, 2023). "Furthermore, treatment with TGFβ1 inhibitor, Disitertide, or TGFβ1 receptor inhibitor, LY-364947, significantly inhibited FAM3C expression in neutrophils, and reversed expression of E-cad and Vim in tumor cells, respectively." (PMID 37056931, 2023). "FAM3C expression in the A549 parental and FAM3C_ox tumor nodules appear to be unipolar or perinulcear in these small tightly packed carcinoma cells and as punctate cytoplasmic positivity proximal to the nuclei in the larger spread carcinoma cells (2, black arrows)." (PMID 36632230, 2023). "The high efficiency of the combined inhibition of c-MET and ILEI function on the inhibition of invasion and tumor growth of cancer cells bearing MET and FAM3C amplifications found in this study justifies the relevance of this co-amplification on clinical outcomes." (PMID 33596971, 2021). "However, a recent research revealed that exogenous FAM3C strictly required co-operation with oncogenic Ras to cause TGF-β-independent EMT and tumor progression in human hepatocytes." (PMID 26498278, 2015). "Therefore, we proposed that tumor cells-derived transforming growth factor-β1 (TGFβ1) may be involved in FAM3C up-regulation in neutrophils." (PMID 37056931, 2023).
tumor (continued). "Previously, we demonstrated that crosstalk between neutrophils and tumour cells is required for enhanced tumour cell invasiveness, and that neutrophils boost the epithelial-to-mesenchymal transition (EMT) of tumour cells via secreting FAM3C." (PMID 38862740, 2024). "FAM3C/ILEI is an important factor in epithelial-to-mesenchymal transition (EMT) induction, tumor progression and metastasis." (PMID 37713409, 2023). "Semi-quantitative measurement of FAM3C using immunohistochemical staining was performed on 45 cases of NSCLC, 47 cases of tumor-adjacent normal tissue, and 8 cases of normal lung tissue." (PMID 36632230, 2023). "The higher expression of FAM3C, LGALS9, ANXA1, SPP1, CD99 and LAMP1 in tumor tissues compared with normal tissues were confirmed by immunohistochemistry in tumors." (PMID 35087839, 2021). "Early research demonstrated that FAM3C alone was sufficient to induce EMT, tumor growth and metastasis in murine mammary epithelium cell EpH4, independently of TGF-β activation." (PMID 26498278, 2015). "Furthermore, research has shown that tumor cells activate neutrophils via TGF-β1, leading to the production of the metabolism-regulating signaling molecule FAM3C through Smad2/3 signaling." (PMID 40387965, 2025). "FAM3C, in turn, promotes EMT in tumor cells via the JNK-ZEB1/Snail signaling pathway." (PMID 40387965, 2025). "PVR/TIGIT, NECTIN2/CD226, and FAM3C/PDCD1 were relatively more strongly expressed in Plac1+ epi‐CD4+ T cells than Plac1− epi‐CD4+ T cells and PVR was specific for Plac1+ tumor cells, which was subsequently validated in HNSCC cells in vitro and in the TMA cohort by mIF." (PMID 40056047, 2025). "Additionally, cells with knocked down ALDH1A3 or the other key genes FAM3C, PMEPA1, and MCC showed reduced tumor xenograft growth and metastasis in mice, highlighting their role in tumor progression." (PMID 40781158, 2025). "Notably, when FAM3C overexpression was combined with DAPT treatment, the tumor size was reduced compared to the overexpression group alone." (PMID 39629744, 2024). "In addition, it was reported that FAM3C can induce the epithelial-to-mesenchymal transition (EMT) process in cancer, which is critical for tumor invasion, metastasis, and recurrence." (PMID 38254989, 2024). "To identify which factor is responsible for tumor EMT induced by Edu-Neus, we found that FAM3C could decrease E-cad expression and increase Vim expression in MKN28 or MKN45 cells with a dose-dependent manner." (PMID 37056931, 2023). "Several proteins that are involved in tumor growth were present in glioblastoma cyst fluid (for references, see “Discussion” section): SPARCL1, IGF-BP2, osteopontin, FAM3C, TREM2, CD166, and prosaposin promote tumor cell proliferation, migration, and invasiveness." (PMID 35659255, 2022). "However, previous studies suggest that several of the identified proteins are potent stimulators of tumor cell proliferation or invasiveness, including SPARCL1, IGF-BP2, osteopontin, FAM3C, TREM2, CD166, prosaposin, and kininogen-1/bradykinin." (PMID 35659255, 2022). "Interleukin-like EMT inducer (ILEI, FAM3C) is a secreted factor that contributes to the epithelial-to-mesenchymal transition (EMT), a cell-biological process that confers metastatic properties to a tumor cell." (PMID 29871931, 2018). "ILEI (FAM3C) is a secreted factor that contributes to the epithelial-to-mesenchymal transition (EMT), a cell biological process that confers metastatic properties to a tumor cell." (PMID 28545079, 2017). "The average level of FAM3C expression in tumor specimens was dramatically higher than that in nontumor specimens (5.72 versus 1.61, P < 0.001, paired Student’s t test)." (PMID 26498278, 2015). "Our previous RNA-seq data showed that FAM3C was overexpressed in all three tested ESCC tumor tissues compared to corresponding nontumor tissues." (PMID 26498278, 2015).
tumor (continued). "Furthermore, overexpressing ALDH1A3 in ALDH1A3-negative PDAC cells (PANC-1/ALDH1A3OE) increased the expression of FAM3C, MCC, and PMEPA1, which was supported by our previous data demonstrating that ALDH1A3 overexpression in PANC-1 cells promoted tumor invasion in vitro." (PMID 40781158, 2025). "In addition to a number of reported mRNA transcripts, such as ILEI, EGFR, MOESIN, FAM3C, JAK2 and EIF5A2, we identified ZEB2, an EMT‐related transcription factor that is vital for tumor metastasis, as a potential transcript regulated by PCBP1 at the translational level." (PMID 41117067, 2025). "Furthermore, blockage of FAM3C with a neutralizing antibody, AB72182, could reverse the enhanced-invasiveness and induced-EMT of tumor cells mediated by Edu-Neus." (PMID 37056931, 2023). "Moreover, PCBP1-AS1 also showed a significant negative correlation with FAM3C, BCL10, SLC16A3, WDR1, and other key molecules of tumor malignant behavior." (PMID 38433921, 2024).
cancer (30 papers, 2015 to 2026). A tumor composed of atypical neoplastic, often pleomorphic cells that invade other tissues. "Cancer-associated fibroblast, macrophage, neutrophil, and natural killer cell-derived miRNAs, together with systemic indices such as the neutrophil-to-lymphocyte ratio and mediators like FAM3C, add microenvironmental layers of EMT regulation." (PMID 41681934, 2026). "However, whether increased expression of ILEI in some cancers is associated with increased CN of the FAM3C locus is unclear." (PMID 33596971, 2021). "Cancer stem cells preferentially expressed the signaling molecule FAM3C induced by the stem cell transcription factor SOX2 to drive expression of proline synthesis enzymes." (PMID 42222882, 2026). "The protein expressed by FAM3C was later shown in the context of cancer to be involved in epithelial-to-mesenchymal transition (EMT)." (PMID 37713409, 2023). "For instance, increased FAM3C copy numbers were correlated with extramural invasion of CRC, and the mechanism investigation revealed FAM3C promoted cancer cell invasion through E‐cadherin transcription." (PMID 36281556, 2023). "Our present study and several other reports 38, 40 showed that FAM3C levels are positively correlated with poor prognosis in cancer patients, making FAM3C as a novel biomarker or potential therapeutic target for cancer." (PMID 37056931, 2023). "Microscopic analyses of the tissue histology revealed that FAM3C is predominantly localized in the cytosol, with strong expression detected in the cancer cells." (PMID 36632230, 2023). "The results of heatmap revealed that FAM3A and FAM3C were commonly highly expressed in pan-cancer tissues." (PMID 37704682, 2023). "It would be important to extend the investigation into these carcinomas to determine the role of FAM3C." (PMID 36632230, 2023). "Metastasis potential of TDEs secreted by FAM3C-overexpressing carcinoma cells was validated in mouse models." (PMID 36632230, 2023). "These lung tumor aggregates were found to express FAM3C (brown) and Ki67 positive cells (red), providing further evidence that FAM3C is an important mediator of carcinoma cell invasion and engraftment." (PMID 36632230, 2023). "In this context, inhibition of RalA would impair EVs trafficking and release, potentially impacting on vesicular FAM3C-mediated carcinoma cell invasiveness." (PMID 36632230, 2023). "As the gene encoding ILEI, FAM3C has been identified as an EMT-specific gene and an emerging biomarker and potential therapeutic target for cancer." (PMID 35093095, 2022). "The results of this study show that amplification of FAM3C CN can contribute to increase the level of ILEI expression in a wide range of cancer types." (PMID 33596971, 2021). "Met, Tspan12, and Fam3c, which are located on DMs, facilitate cancer malignancies, and are correlated with poor prognosis." (PMID 29497033, 2018). "Consequently, targeting FAM3C functions emerges as a promising therapeutic strategy for FAM3C‐driven cancers." (PMID 39629744, 2024). "FAM3C exhibits a variety of functions across different disease types, suggesting that it may operate through distinct signaling pathways in various cancers." (PMID 39629744, 2024). "The multifunctionality and variability in FAM3C mechanisms across different cancers might limit its application as a specific biomarker for GBM, and its broad mechanistic role as a therapeutic target could pose unpredictable side effects." (PMID 39629744, 2024). "In contrast, the aggressiveness of the FAM3C_ox cancer cells in near complete colonization the host lungs compared to the A549 ctrl and FAM3C_kd cells further supports our hypothesis that FAM3C is a potent inducer of cancer metastasis and disease progression." (PMID 36632230, 2023). "Given the known role of FAM3C in promoting EMT in a few cancers, we hypothesized that FAM3C carried on TDEs could promote proliferation of NSCLC at secondary sites." (PMID 36632230, 2023).
cancer (continued). "We next explored strategies in targeting FAM3C-driven cancers." (PMID 36632230, 2023). "Meanwhile, among the FAM3 family genes FAM3C had the highest expression in pan-cancer tissues." (PMID 37704682, 2023). "On the one hand, the results above showed that FAM3C expression was highest in pan-cancer." (PMID 37704682, 2023). "The aim of this study was to investigate whether increased FAM3C CN was evident in various cancers and reveal whether there was a relationship with MET amplification." (PMID 33596971, 2021). "All these data show that MET amplification has broad relevance in many cancers and our study indicates that FAM3C co-amplification may play a comparably important role in all these different cancer types." (PMID 33596971, 2021). "FAM3C expression is upregulated in several cancers, and circulating FAM3C level could also be a biomarker for autophagy and some cancers." (PMID 29285313, 2017). "To unravel the clinical significance of FAM3C in carcinomas, we began by delineating its clinicopathological and molecular correlation by leveraging on publicly available transcriptomic datasets as well as immunohistochemical evaluation of FAM3C expression in tissue microarrays." (PMID 36632230, 2023). "As a cytokine-like gene, FAM3 family includes FAM3A, FAM3B, FAM3C, and FAM3D, and is involved in the occurrence and development of several cancers." (PMID 37056931, 2023). "Having shown that FAM3C promotes EMT and cancer aggressiveness in vitro, we wonder if changes in intracellular FAM3C translates to any appreciable effects in vivo." (PMID 36632230, 2023). "FAM3C, called interleukin-like EMT inducer (ILEI), is a secreted factor that is involved in TGF-β-mediated EMT and has been found to promote metastasis in several types of cancer." (PMID 35406721, 2022). "Myeloid cell-cancer cell communication analyses revealed activation of C5AR1/RPS19 and HLA-C/FAM3C pairs." (PMID 34326696, 2021). "To determine the frequency of CN amplification of the FAM3C and MET genes, we investigated a variety of datasets of different cancer entities from the TCGA database." (PMID 33596971, 2021). "Family with sequence similarity three member C (FAM3C) (interleukin‐like EMT inducer [ILEI]), heat shock factor 1 (HSF1) and Ying‐Yang 1 (YY1) have been independently reported to be involved in the pathogenesis of various cancers." (PMID 30887707, 2019). "The upregulation of CD274 (PD-L1), FAM3C, and other T cell exhaustion markers in NRF2 activated LUAD cancer suggest that they could be the population who can benefit the most from anti-PD1 or anti-PD-L1 therapy." (PMID 38241355, 2024). "Given its involvement in multiple cancers, relying solely on FAM3C as a prognostic marker for GBM may lack specificity, as its functional mechanisms in other cancers could interfere." (PMID 39629744, 2024). "Interactions of several ligand-receptor pairs between cancer cells and immune cells (CD274:PDCD1, FAM3C:PDCD1, PVR:TIGIT) are predicted to be enhanced in NRF2 signature high samples which could be potential targets to inhibit to remodel the TME." (PMID 38241355, 2024). "In addition, the interactions of KIR2DL3 and FAM3C, and KLRB1 and CLEC2D were detected between cancer cells and T & NK cells." (PMID 37945567, 2023). "Once we had established that MET and FAM3C were often co-amplified and this led to combined overexpression of c-MET and ILEI, it was important to investigate whether they interact during cancer progression." (PMID 33596971, 2021). "The gene for ILEI, FAM3C, is located close to MET on chromosome 7q31 in an amplification “hotspot”, but it is unclear whether FAMC3 amplification contributes to elevated ILEI expression in cancer." (PMID 33596971, 2021).
infection (2 papers, 2019 to 2024). The state of being infected such as from the introduction of a foreign agent such as serum, vaccine, antigenic substance or organism. "For study 2, LASSO selected five proteins, of which LILBR1 and FAM3C were elevated in the group representing the early phase of the infection." (PMID 38565620, 2024). "Similarly, Ad‐FAM3C infection also up‐regulated the expression levels of YY1 and HSF1 mRNAs and proteins with Akt activation when compared with Ad‐GFP–treated cells." (PMID 30887707, 2019).
FAM3C also shares sentences with these, for which no sentence is quoted: breast tumor (2 papers); colon carcinoma (2); hepatocellular carcinoma (2); Insulin resistance (2); metastatic melanoma (2); adenocarcinoma (1); alcoholic liver diseases (1); atopic dermatitis (1); autism spectrum disorder (1); Coffin-Siris syndrome (1); colorectal adenocarcinoma (1); COVID-19 (1); epithelial dysplasia (1); Glucose intolerance (1); Hepatitis (1); Huntington disease (1); hypochromic anemia (1); inflammatory skin disease (1); invasive breast carcinoma (1); liver cancer (1); liver dysfunction (1); liver fibrosis (1); lupus erythematosus (1); mycosis fungoides (1); neonatal diabetes mellitus (1); non-alcoholic fatty liver disease (1); non-small cell lung carcinoma (1); oesophageal cancer (1); oral squamous cell carcinoma (1); ovarian carcinoma (1).
A further 4 diseases each share a sentence with FAM3C in 1 paper.